GOLGB1 (golgin B1)
Description:
May participate in forming intercisternal cross-bridges of the Golgi complex.
Synonyms: GCP372; GCP; giantin; GOLIM1
Tractability: Antibody: UniProt predicts a signal peptide or a membrane-spanning region. PROTAC: ubiquitination databases record sites on it; its protein half-life has been measured.
Gene: Protein-coding gene on chromosome 3 (121,663,199 to 121,749,966, reverse strand). Ensembl gene ENSG00000173230.
Subcellular location: Golgi apparatus membrane
Subcellular location (Human Protein Atlas): Golgi apparatus
Pathways (Reactome):
Vesicle-mediated transport: COPI-mediated anterograde transport; Golgi Associated Vesicle Biogenesis
Disease: Signaling by FLT3 fusion proteins
Gene Ontology:
Molecular function: protein binding; RNA binding; sequence-specific DNA binding
Biological process: protein localization to pericentriolar material; Golgi organization; regulation of DNA-templated transcription
Cellular component: endoplasmic reticulum-Golgi intermediate compartment; Golgi apparatus; membrane; cis-Golgi network; cytosol; Golgi membrane; Golgi stack
Genetic constraint (gnomAD): Loss-of-function variants: 108 observed, 255.28 expected, observed/expected ratio (o/e) 0.42, 90% interval 0.36 to 0.5. The upper end of that interval is the gene's LOEUF score, 0.5, which puts it in group 2 of 6, group 1 being the genes least tolerant of losing a copy. Missense variants: 2,721 observed, 3,119.4 expected, observed/expected ratio (o/e) 0.87, 90% interval 0.84 to 0.9. Synonymous variants: 1,004 observed, 1,122.2 expected, observed/expected ratio (o/e) 0.89, 90% interval 0.85 to 0.94.
Homologues: Orthologues: chimpanzee GOLGB1 (99% identical), macaque GOLGB1 (96% identical), dog GOLGB1 (86% identical), pig GOLGB1 (86% identical), rabbit GOLGB1 (83% identical), guinea pig GOLGB1 (79% identical), mouse Golgb1 (75% identical), rat Golgb1 (75% identical), tropical clawed frog golgb1 (33% identical), zebrafish golgb1 (27% identical), Caenorhabditis elegans syp-1 (4% identical).
Diseases named in the same sentence as GOLGB1 in open-access papers:
GOLGB1 is named in the same sentence as 22 diseases in open-access papers, as found by Europe PMC text mining. Sharing a sentence is not in itself a finding about the gene and the disease. The quoted sentences say what the papers report.
cleft palate (3 papers, 2020 to 2024). Cleft palate is a fissure type embryopathy that affects the soft and hard palate to varying degrees. "A report showed that in the process of mammalian organ formation, golgin subfamily B member 1 (Golgb1) mutant embryos caused cleft palate in mice, which was due to reduce hyaluronan accumulation and impair protein glycosylation in the palatal mesenchyme." (PMID 36590585, 2022). "A previous study reported that the GOLGB1 loss-of-function mutation was co-segregated with cleft palate, and GOLGB1 mutant embryos showed intrinsic defects in palatal shelf elevation." (PMID 32178328, 2020).
osteochondrodysplasia (3 papers, 2015 to 2022). A term referring to disorders characterized by abnormalities in the development of bones and cartilage. "Homozygous knockout (KO) rats, possessing a null mutation in the Golgb1 gene, which encodes giantin, develop late embryonic lethal osteochondrodysplasia." (PMID 29093022, 2017). "In addition, homozygous loss of function mutation of Golgb1 leads to several osteochondrodysplasia and late embryonic lethality in rats but only cleft palate in mice, suggesting that GOLGB1 may regulate osteogenesis and/or chondrogenesis." (PMID 36115840, 2022).
prostate carcinoma (3 papers, 2021 to 2025). A carcinoma that arises from epithelial cells of the prostate gland. "In 2014, GOLGB1 was reported to enhance susceptibility to galectin-1 in prostate cancer, thereby inducing cellular apoptosis." (PMID 40657366, 2025). "Reduced GOLGB1 expression has been reported to promote the progression of prostate cancer." (PMID 34793335, 2022).
breast carcinoma (2 papers, 2020 to 2025). "Recent research also demonstrates that GOLGB1 plays a critical role in the risk of pulmonary metastasis among breast cancer patients." (PMID 40657366, 2025). "Finally, 6 genes (GOLGB1, TMEM158, CXCL8, MCM5, HIF1AN, and TSPAN31) were selected that could optimally predict the lung metastasis risk of breast cancer patients." (PMID 33378415, 2020).
ciliopathies (2 papers, 2017 to 2022). "Mutations in Golgb1, the gene encoding GIANTIN, or loss-of-function models display morphological alterations reminiscent of ciliopathies." (PMID 36139347, 2022).
depression (2 papers, 2013 to 2022). "Still, we were able to confirm the segregation of one of these variants (rs140932474 in the gene GOLGB1) with symptoms of depression in a second bipolar family sequenced in our laboratory." (PMID 24348429, 2013).
Stroke (2 papers, 2015 to 2021). Sudden impairment of blood flow to a part of the brain due to occlusion or rupture of an artery to the brain. "Three genes (orange), golgin subfamily B member 1 (GOLGB1), α-galactosidase A (GLA), and heme oxygenase-1 (HMOX1), are both SARS-CoV-2 host genes as well as stroke-associated genes." (PMID 33732102, 2021).
atherosclerosis (1 paper, 2015). A disease characterized by the build-up of fatty material and calcium deposition in the arterial wall resulting in partial or complete occlusion of the arterial lumen. "Multiligand receptor for advanced glycation end products (RAGE), osteoprotegerin, and Golgb1 genes may be implicated in atherosclerosis and vascular diseases." (PMID 26664786, 2015).
bladder cancer (1 paper, 2017). "Indeed, GOLGB1 mutation was frequently observed in lung cancers (9%), while the SF3B3 mutation was frequently observed in bladder cancer (5.4%)." (PMID 28038442, 2017).
colorectal cancer (1 paper, 2025). A primary or metastatic malignant neoplasm that affects the colon or rectum. "We systematically analyzed the prognostic value of transcription levels of SFs in colorectal cancer (CRC) and found that RAB3A interacting protein (RAB3IP), programmed cell death 4 (PDCD4), golgin B1 (GOLGB1), and neuregulin 4 (NRG4) as the most predictive markers for the prognosis of CRC." (PMID 40657366, 2025).
hemorrhagic stroke (1 paper, 2015). A stroke caused by a bleed on the brain. "Single nucleotide polymorphisms (SNPs) rs1035798 in RAGE gene, rs2073617 and rs2073618 in TNFRSF11B, and rs3732410 in Golgb1 will be investigated on whether there is an association with hemorrhagic stroke (HS) in Chinese population." (PMID 26664786, 2015).
liver cancer (1 paper, 2017). An epithelial or non-epithelial malignant neoplasm that arises from the liver. "Both the knockdown cells for GOLGB1 or SF3B3 suppressed cell proliferation activity in diverse liver cancer cell lines of HepG2, Huh7, Hep3B, SNU423, and PLC." (PMID 28038442, 2017). "By performing experimental evaluation using siRNA-mediated knockdown and overexpression constructs, we demonstrated that the mutants of GOLGB1 and SF3B3 can promote cell proliferation, colony formation, migration, and invasion of liver cancer cells." (PMID 28038442, 2017). "In addition, we could observe positive correlations of the expression levels of GOLGB1 or SF3B3 with the expression levels of CXCL8 and SOX4 in the liver cancer data of TCGA, implying the potential connection between them." (PMID 28038442, 2017).
neuropathies (1 paper, 2020). "DNAH3 is a type of dynein involved in producing force for ciliary beating by using energy from ATP hydrolysis, and GOLGB1 is a widely expressed large coiled-coil protein and Golgi integral membrane protein associated with neuropathies." (PMID 33352926, 2020).
osteosarcoma (1 paper, 2025). A usually aggressive malignant bone-forming mesenchymal neoplasm, predominantly affecting adolescents and young adults. "In this study, mouse osteosarcoma K7M2 cells were analyzed and several highly immunogenic neoantigens (Golgb1 and Phf14) were identified." (PMID 39742319, 2025).
tumor (4 papers, 2020 to 2025). "GOLGB1 (golgin B1) is reported to be involved in the process of the Golgi affecting tumor progression and metastasis." (PMID 33378415, 2020).
cancer (2 papers, 2017 to 2020). A tumor composed of atypical neoplastic, often pleomorphic cells that invade other tissues. "We demonstrated that the overexpression of the GOLGB1 or SF3B3 promoted aggressive cancer progression such as cell proliferation, invasion, and migration reflecting aggressive behaviors of the recurrent HCC." (PMID 28038442, 2017). "In addition, GOLGB1 possessed the most frequent genetic alterations (9%) in cBioPortal for Cancer Genomics." (PMID 33378415, 2020).
GOLGB1 also shares sentences with these, for which no sentence is quoted: Anxiety (1 paper); bipolar disorder (1); familial tumoral calcinosis (1); fibrodysplasia ossificans progressiva (1); lung carcinoma (1); pulmonary arterial hypertension (1).